MMP2 (matrix metallopeptidase 2)
Diseases named in the same sentence as MMP2 in open-access papers (continued):
Sharing a sentence is not in itself a finding about the gene and the disease.
prostate carcinoma (continued). "It has also been reported that MMP-2 is one of miR-29b targets in Hela cells and prostate cancer cells." (PMID 21573166, 2011). "Our present finding from the investigation of clinical materials indicates that there is a direct link between cystatin C and extracellular matrix protein MMP2 in prostate cancer." (PMID 19956729, 2009). "Both MMP2 and MMP-9, in particular, have been found to be associated with prostate cancer metastasis." (PMID 19956729, 2009). "Overexpression of E-cadherin decreased MMP-2 activity in prostate cancer cells and MT1-MMP in squamous cancer cells." (PMID 19636436, 2009). "In particular, MMP-2 and MMP-9 have been suggested to be associated with prostate cancer metastasis, as high levels of these proteins were measured in plasma and urine in patients with metastatic disease." (PMID 19956729, 2009). "Using the scid-hu model for bone metastasis, in which human prostate cancer cells are grown in human bone xenografts in scid mice 16, we confirmed high expression of mmp-2 and mmp-9 in cancer cells and in neighbouring bone stromal cells." (PMID 18769612, 2008). "Previously, Meyer-Siegler and coworkers showed a positive correlation between MIF and MMP-2 in prostate cancer cells." (PMID 16872482, 2006). "Addition of MIF to proliferating DU-145 prostate cancer cells resulted in a twofold increase in the relative amount of active MMP-2." (PMID 16872482, 2006). "Furthermore, research has revealed that polymorphic genetic variations in the MMP2 gene significantly contribute to the initiation and progression of prostate cancer." (PMID 40533843, 2025). "HDAC1 could induce the activation of urokinase-type plasminogen activator (uPA), matrix metalloprotease-1 (MMP-1) and MMP-2, but suppressed E-cadherin in order to accelerate the invasion and migration of prostate cancer cells." (PMID 38800374, 2024). "Consequently, upregulated MMP-2 secretion by metastatic prostate cancer cells can promote platelet aggregation." (PMID 39796673, 2024). "In addition, equol can also inhibit invasion of DU145 prostate cancer cells by downregulating matrix metalloproteinase 2 (MMP-2) and MMP-9." (PMID 38972976, 2024). "Furthermore, corroborating evidence of genisteins MMP-2 reduction has emerged from other scientific investigations, not only in prostate cancer but also in breast cancer and glioblastoma cell lines." (PMID 38939095, 2024). "In addition, various studies have demonstrated that genistein can inhibit tumor cell metastasis via blocking the activation of MMP-2 and the phosphorylation of focal adhesion kinase in human prostate cancer cells." (PMID 36794010, 2023). "This suggests that SIRT1 upregulates MMP2 activity to promote the progression of prostate cancer." (PMID 36291902, 2022). "Furthermore, ibrutinib decreased the synthesis of matrix metalloproteinases-2 and -9 (MMP-2 and MMP-9)—endopeptidases, of which overexpression is associated with increased invasiveness and severity of prostate cancer." (PMID 35456016, 2022). "In addition, SIRT1 overexpression led to enhanced expression of MMP2, promoting cell invasion in prostate cancer cells." (PMID 35252011, 2022). "Racially disparate expression of MMP2 and 9 has been reported in AA prostate cancer patients." (PMID 33996789, 2021). "In prostate cancer tissues, large oncosomes harbor abundant bioactive molecules involved in local invasion including MMP2 and 9, while microvesicles shed by tumor cells are reported to deliver matrix ECM inducer (EMMPRIN) to fibroblasts, promoting tumor invasion and metastasis." (PMID 33809973, 2021). "Intriguingly, highly abundant exosomal miRNAs such as miR-100-5p, miR-21-5p, and miR-139-5p from prostate cancer stem cells increased MMP2, 9, 13 and RANKL expression and enhanced the migration of fibroblasts, contributing to local invasion and pre-metastatic niche formation." (PMID 33809973, 2021).
prostate carcinoma (continued). "Furthermore, it was shown that the MMP2 activity of the prostate cancer cell line DU 145 was significantly higher in comparison to L-cells (sevenfold higher)." (PMID 34067049, 2021). "Interestingly, while both bacterial neuraminidase and T. cruzi sialidase activate only MMP-2, the mammalian sialidase Neu-3, specific for SA α2,3 recognition observed in human prostate cancer models, is able to modulate both MMP-2 and MMP-9." (PMID 33891967, 2021). "In addition, AA-derived prostate cancer cell lines showed higher expression of MMP2 and MMP9 both at transcriptome and proteome levels compared to CA counterparts." (PMID 33996789, 2021). "To examine whether the prostate cancer cell migration and invasion were associated with the EMT, we detected the expression of EMT related proteins, including MMP-2, vimentin and E-cadherin in PC-3 and DU145 cells." (PMID 33613773, 2021). "Silibinin, a flavanone isolated from milk thistle, decreased vimentin protein expression in a dose- and time-dependent manner and suppressed MMP-2 expression, while it regulated cytokeratin-18 gene in ARCaPM cells, an in vitro model of prostate cancer progression to bone metastasis." (PMID 34572548, 2021). "Consistent with previous observations, we demonstrated that ZKSCAN3 silencing in prostate cancer lines resulted in significant reduction of cell viability, colony formation, cell migration, cell invasion, and the expression of MMP2/MMP9, as well as significant induction of apoptosis." (PMID 32824199, 2020). "The other possible candidates for increased MMP-2 value might be free miRNA from PEVs lysate or lysophosphatidic acid (LPA) as an MMP-2 activator presented on PLTs and in prostate cancer cells." (PMID 32707975, 2020). "Consistently, the radial repositioning patterns of FLI1, MMP9 and MMP2 also do not correlate with the risk/aggressiveness of prostate cancer." (PMID 31681438, 2019). "During prostate cancer progression the level of enzymes involved in metastasis, uPA, MMP-2, and MMP-9, displayed increased levels in the dorsolateral prostate of TRAMP mice, but the intake of apigenin downregulated their levels, which led to a “complete absence” of the metastasis." (PMID 30823649, 2019). "MMP-2 expression is downregulated in human prostate cancer cells by genistein treatment." (PMID 31781485, 2019). "Genistein could bind to and inhibit mitogen-activated protein kinase kinase 4 (MEK4) kinase activity in prostate cancer cells, which in turn attenuated matrix metalloproteinase-2 (MMP-2) expression and reduced cell invasion." (PMID 29743815, 2018). "One of these MMPs is MMP-2, which may be involved in prostate cancer (PCa) progression and metastasis." (PMID 29440967, 2018). "Matrix metalloproteinases (MMPs) are involved in tumor progression, and treatment with 10.9–87.3 μM EGCG inhibited fibroblast conditioned medium (FCM)-induced phosphorylation of ERK1/2 and/or p38 concomitant reduction in MMP-2 and -9 in human prostate carcinoma DU-145 cells." (PMID 28942499, 2017). "Furthermore, certain single-nucleotide polymorphism (SNP) mutations of the MMP2 gene, especially at position −1306 of the MMP2 promoter (rs243865), function as regulatory factors in the formation and metastasis of prostate cancer." (PMID 29069837, 2017). "Therefore, we aimed to perform a meta-analysis to shed some light on the controversial conclusion pertaining to the associations of MMP-2-1306 C/T and MMP-1-1607 1G/2G polymorphisms with prostate cancer susceptibility." (PMID 29249982, 2017). "PMPs promote invasion of prostate cancer cells by up-regulating MMP-2." (PMID 29228624, 2017). "The MMP-2 expression level was significantly correlated with the tumor grade of prostate cancer." (PMID 27340864, 2016). "For example, high MMP-2 expression is observed in prostate cancer compared with benign lesions." (PMID 27340864, 2016). "Matrix metallopeptidase-2 (MMP-2) has been identified as a miR-29b target in prostate cancer cells." (PMID 27588490, 2016).
prostate carcinoma (continued). "Together, these data suggest that, similar to genetic knockdown, pharmacological inhibition of PBK strongly reduces two hallmarks of cancer in prostate cancer cells, namely, invasive ability, via down-regulation of β-catenin-mediated production of MMP-2 and -9, and proliferation." (PMID 25909225, 2015). "A fractional extract obtained from American ginseng plant has been demonstrated to have anti-cancer properties in colorectal cancer and its mechanism of drug action was discovered to be due to the overexpression of miR-29b, which regulates MMP-2 expression as was observed in prostate cancer." (PMID 24670365, 2014). "Increased expression of MMP-2 has been extensively reported in prostate cancer and higher MMP-2 expression has been correlated with larger tumor size, higher Gleason score and more advanced pathological TNM stage (a clinical cancer staging system used to describe the extent of a person’s cancer)." (PMID 24978435, 2014). "Besides, its function as a proapoptotic protein, secretory Par-4 is reported to regulate MMP-2-mediated motility in cervical and prostate cancer in response to 3-azido Withaferin A." (PMID 24523904, 2014). "RUNX3 suppresses prostate cancer metastasis due to the imbalance between MMP-2 and TIMP-2." (PMID 24475196, 2014). "And finally CDK11p58 could inhibit the metastasis of AR positive prostate cancer cells through inhibition of integrin β3 and MMP2." (PMID 24397471, 2014). "However, in vitro studies showed that NGAL plays a significant role in the progression of prostate cancer by regulating MMP2 and MMP-9." (PMID 24742531, 2014). "In addition, serum MMP-2 levels correlated with the clinical course of prostate cancer with bone metastasis." (PMID 24978435, 2014). "Conditioned media collected from an estradiol-treated immortalized prostatic stromal cell line WPMY-1 and primary stromal cells promoted invasion of prostate cancer cells in a paracrine mechanism by up-regulating MMP-2 expression at both mRNA and protein levels." (PMID 24978435, 2014). "In addition, there was an overall increase in secreted MMP-2 (latent) as commonly noted in invasive prostate cancer cells." (PMID 21219645, 2011). "Expression of MMP-2 and MMP-9 are associated with prostate cancer progression." (PMID 21629786, 2011). "MMP-2 and MMP-9 are associated with metastasis of prostate cancer cells to bone." (PMID 17343740, 2007). "It is possible that MMP-2 can be activated by different signaling pathway in prostate cancer cells." (PMID 17343740, 2007). "Other studies using a human prostate cancer cell line (DU-145) or a colorectal cancer cell line (MC-26), treated with 10 and 100 μM NS-398, reported a reduction in the release of pro and active MMP-2 and MMP-9 in the culture media." (PMID 16831226, 2006). "Elevated plasma MMP-2 activity has also been suggested to be prognostic for prostate cancer metastasis, indicating that there may be a discrepancy between MMP2 RNA and protein levels in prostate tumours." (PMID 15928670, 2005). "The data suggest that cytokine upregulation of TIMP-1 and coordinate downregulation of MMP-2 expression might control the molar ratio of TIMP-1 and MMP-2 to influence the level of protease activity and invasive behaviour of malignant prostate cancer cells." (PMID 12771930, 2003). "A randomized phase II trial (NCT01126879) determined whether treatment with genistein could reduce the number of circulating prostate cancer cells and tumor growth via the downregulation of the expression of factors promoting tumor growth, including MMP-2, in prostate tissue." (PMID 39335164, 2024). "A previous report showed that LIMK1 could increase MMP2 expression in prostate cancer." (PMID 34079084, 2021). "Western blotting assay further indicated that CCL5 could induce epithelial-mesenchymal transition (EMT) in both prostate cancer cells, characterized by the decreased expression of E-cadherin as well as the increased expression of N-cadherin, Vimentin, MMP2, and MMP9." (PMID 32300100, 2020).
prostate carcinoma (continued). "However, decreased expression of microRNA-29b (miR-29b), which may control MMP-2 and collagen gene expression, has been shown in prostate cancer (PCa)." (PMID 29440967, 2018). "In summary, our findings suggest that the MMP-2-1306 C/T polymorphism is associated with elevated risk of prostate cancer, but MMP-1-1607 1G/2G polymorphism may have an inhibitory effect on the risk of prostate cancer in Caucasians." (PMID 29249982, 2017). "Moreover, in prostate cancer cells, RhoC activates matrix metallo‐proteinases 2 and 9 (MMP2 and MMP9) in vitro, which could contribute to invasion." (PMID 25677806, 2015). "Interaction between CCR1 and CCL5 promotes the invasion of taxane-resistant PC3 prostate cancer cells by increasing the secretion of MMP-2 and -9 via ERK and Rac activation suggesting that CCR1 could be a novel therapeutic target for taxane-resistant prostate cancer." (PMID 24523569, 2014). "SB225002 reduced the invasion ability of prostate cancer cells by inhibiting the expression of BSP, OPN, and MMP-2 proteins." (PMID 41155662, 2025). "A pre-metastatic conditioning study using exosomes derived from hypoxic prostate cancer cells revealed the highest MMP (MMP9 and MMP2) activity in prostate cancer target metastatic organs, such as the liver, kidney, and spleen." (PMID 41463352, 2025). "Still, they also found that the phosphorylation of genes like FAK reduced metalloproteases (MMP2 and MMP9), decreasing breast and prostate cancer cell invasion by promoting PIK-Akt pathway activity and keeping Nf-kB in the cytoplasm of the cancer cell." (PMID 39063176, 2024). "LYC inhibits EGF-induced JAK/STAT signaling as well as various downstream STAT3 targets, such as cyclin D1, Bcl-2, Bcl-xL, matrix metalloproteinase 2 (MMP2), and the EMT promoter Twist, which lowers prostate cancer cell line proliferation, migration, invasion." (PMID 38572428, 2024). "In prostate cancer, OGT ablation reduces the expression of angiogenic factors, such as vascular endothelial growth factor, matrix metallopeptidase 2 (MMP2), and MMP9, to block angiogenesis." (PMID 39178944, 2024). "Similar downregulation of MMP-2 and MMP-9 levels has been observed in prostatic carcinoma by inhibiting the signaling of JNK, PI3K, Akt to reduce NF-κB and AP-1 DNA-binding activities." (PMID 38611849, 2024). "A decrease in the induction of MMP-2 and cell migration following a block in the phosphorylation of MAP kinase p38 was observed upon in vitro and in vivo treatment of prostate cancer cells with the isoflavone genistein." (PMID 38540096, 2024). "The effective inhibition of MMP-2 and MMP-9 activity and cell migration was also verified in DU145 prostate cancer cells using a Psidium guajava leaf extract rich in rutin and quercetin, which were also the dominant components of our tested extracts." (PMID 39683504, 2024). "In this case, the gelatinolytic activity of metalloproteases 2 (MMP2) and 9 (MMP9) is assessed by zymography, as they are the MMPs most involved in the progression of prostate cancer." (PMID 39456984, 2024). "Taken together, HA has an efficacy to suppress the migratory and invasion potential of prostate cancer PC3 and LNCaP cells as well as overexpressing RUNX1 in PC3 cells via the downregulation of MMP2 and MMP9." (PMID 37367670, 2023). "Annexin A5, one of the exosome proteins in prostate cancer tissues, activates AKT signaling to stimulate the epithelial–mesenchymal transition (EMT) and upregulate matrix metalloproteinase-2 (MMP2) and MMP9 expression." (PMID 36612314, 2023). "Our group confirmed that exposure of PC3 cells to resistin increases the secretion level of MMP-2 and MMP-9 in the conditioned medium, favoring invasion in prostate cancer cells." (PMID 38137922, 2023). "PEITC-mediated up-regulation of miR-194 was due to the reduced expression of MMP-2 and MMP-9 through targeting BMP1 in prostate cancer cells." (PMID 36765652, 2023).
prostate carcinoma (continued). "PEITC also promoted the suppression of the expression of MMP2 and MMP9 proteins, which in turn attenuated tumor invasion and cell migration in prostate cancer cells." (PMID 36765652, 2023). "The release of mature epiregulin occurs via proteolytic cleavage by ADAM17, MMP2, and MMP9 which are increased in castration-resistant prostate cancer cells." (PMID 36994208, 2023). "Prostate-cancer-cell-derived exosomal miR-139-5p and miR-21-5p remodeled ECM by promoting MMP-2 and MMP-13 expression in stromal cells, thereby contributing to PMN formation and distant metastasis of prostate cancer." (PMID 37046819, 2023). "ADAM17 targets MMP2 and MMP-9 via EGFR-MEK-ERK pathway activation to promote prostate cancer cell invasion." (PMID 36172139, 2022). "Generally, proteolytic degradation of extra-cellular matrix (ECM) is mediated by MMPs, with MMP-2 and MMP-9 playing a critical role in prostate cancer progression." (PMID 36497399, 2022). "As anti-cancer agent, rubimaillin suppresses Notch signaling to down-regulate MMP-2 and MMP-9 expressions in inhibiting growth and invasion of prostate cancer cells." (PMID 35773731, 2022). "Several studies in prostate cancer, sarcoma, and fibroblast cells have shown that activation of MEK/ERK signaling promoted the expression of MT1-MMP and MMP2." (PMID 35729527, 2022). "In colorectal and prostate cancers, HNRNPK in the nucleus enhance the transcriptional activity of MMP2 to facilitate cell invasion." (PMID 36439880, 2022). "Notch1 can promote expression levels of MMP-2 and MMP-9 in increasing progression and metastasis of prostate cancer cells." (PMID 35773731, 2022). "Anti-cancer activity of quercetin such as induction of apoptosis, fatty acid synthase (FAS), inhibition of cell proliferation, reduction of metalloproteinase-2 (MMP-2), and metalloproteinase-9 (MMP-9) expression in prostate cancer cells were studied." (PMID 35971151, 2022). "SFN alone or in combination with quercetin or GTC decreased the expression of matrix metalloproteinase-2 (MMP-2) and MMP-9, which are known to be potent triggers of prostate cancer metastasis." (PMID 34835969, 2021). "It is well established that increased expression of MMP-2 and MMP-9 have been evaluated as prognostic marker in BC and prostate cancer." (PMID 34315513, 2021). "Inhibition of SENP1 expression in high-grade metastatic prostate cancer cells can affect the bone remodeling ability of HIF-1α and its downstream matrix metalloproteinase (MMP)-2 and MMP-9, and then inhibit the bone metastasis of prostate cancer cells." (PMID 33791211, 2021). "For example, an increase in the expression of the Ca2+ channels TRPV2 in prostate cancer, and TRPM8 in squamous cell carcinoma resulted in induction of MMP-2 and MMP-9, respectively." (PMID 33802790, 2021). "Since the inhibitory effect of RSV on MMPs has been shown in many cancer types, and RSV is capable of inhibiting both MMP-2 and MMP-9, the inhibitory effect of RSV on prostate cancer was examined in different models." (PMID 33535458, 2021). "Following the curcumin treatment in a xenograft model of prostatic cancer, MMP-9 and MMP-2 expression remarkably decreased." (PMID 34456716, 2021). "The stromal-cell–secreted MMPs play an indispensable role in cancer cell metastasis, with MMP-2 and MMP-9 being the best-studied MMPs in prostate cancer metastasis." (PMID 33535458, 2021). "In addition, siRNA silencing of TRPV2 reduced the growth and invasion of PC-3 cells in xenograft models of prostate cancer and reduced the expression of invasive markers, MMP2, MMP9, and cathepsin-B, suggesting that inhibition of TRPV2 may reduce the aggressive phenotype of prostate cancer." (PMID 32825277, 2020). "SENP1 can regulate MMP-2 and MMP-9 through the HIF1α signaling pathway, thereby promoting the progression of prostate cancer cell lines and bone metastasis." (PMID 33123273, 2020).